SNORD56B (small nucleolar RNA, C/D box 56B)
Synonyms: RNU56B
Gene: Small nucleolar RNA gene on chromosome 14 (71,398,337 to 71,398,407, forward strand). Ensembl gene ENSG00000207444.
Gene Ontology:
Biological process: RNA processing
Cellular component: nucleolus
Homologues: Orthologues: macaque SNORD56B (93% identical). Paralogues in human: SNORD56 (89% identical).